BMP7 (bone morphogenetic protein 7)
Description:
Growth factor of the TGF-beta superfamily that plays important role in various biological processes, including embryogenesis, hematopoiesis, neurogenesis and skeletal morphogenesis. Initiates the canonical BMP signaling cascade by associating with type I receptor ACVR1 and type II receptor ACVR2A. Once all three components are bound together in a complex at the cell surface, ACVR2A phosphorylates and activates ACVR1. In turn, ACVR1 propagates signal by phosphorylating SMAD1/5/8 that travel to the nucleus and act as activators and repressors of transcription of target genes. For specific functions such as growth cone collapse in developing spinal neurons and chemotaxis of monocytes, also uses BMPR2 as type II receptor. Can also signal through non-canonical pathways such as P38 MAP kinase signaling cascade that promotes brown adipocyte differentiation through activation of target genes, including members of the SOX family of transcription factors. Promotes the expression of HAMP, this is repressed by its interaction with ERFE.
Synonyms: OP-1
Tractability: Antibody: its Gene Ontology location is reachable by antibodies, with high confidence; UniProt places it where antibodies can reach, with medium confidence; UniProt predicts a signal peptide or a membrane-spanning region. PROTAC: ubiquitination databases record sites on it.
Gene: Protein-coding gene on chromosome 20 (57,168,753 to 57,266,641, reverse strand). Ensembl gene ENSG00000101144.
Subcellular location: Secreted
Subcellular location (Human Protein Atlas): Vesicles; Nucleoplasm; Predicted to be secreted
Pathways (Reactome):
Developmental Biology: Transcriptional regulation of brown and beige adipocyte differentiation by EBF2
Extracellular matrix organization: Molecules associated with elastic fibres
Gene Ontology:
Molecular function: BMP receptor binding; growth factor activity; protein binding; cytokine activity; heparin binding
Biological process: BMP signaling pathway; cellular response to BMP stimulus; mesenchymal cell differentiation; mesonephros development; metanephros development; monocyte aggregation; negative regulation of cell cycle; negative regulation of DNA-templated transcription; negative regulation of glomerular mesangial cell proliferation; negative regulation of mitotic nuclear division; negative regulation of neuron differentiation; neuron projection morphogenesis; osteoblast differentiation; positive regulation of bone mineralization; positive regulation of brown fat cell differentiation; positive regulation of dendrite development; positive regulation of DNA-templated transcription; positive regulation of gene expression; positive regulation of heterotypic cell-cell adhesion; positive regulation of hyaluranon cable assembly; positive regulation of osteoblast differentiation; positive regulation of SMAD protein signal transduction; allantois development; cardiac muscle tissue development; cardiac septum morphogenesis; and 31 more
Cellular component: extracellular region; extracellular matrix; vesicle
Genetic constraint (gnomAD): Loss-of-function variants: 12 observed, 37.19 expected, observed/expected ratio (o/e) 0.32, 90% interval 0.21 to 0.52. The upper end of that interval is the gene's LOEUF score, 0.52, which puts it in group 2 of 6, group 1 being the genes least tolerant of losing a copy. Missense variants: 467 observed, 586.8 expected, observed/expected ratio (o/e) 0.8, 90% interval 0.74 to 0.86. Synonymous variants: 248 observed, 241.59 expected, observed/expected ratio (o/e) 1.03, 90% interval 0.93 to 1.14.
Homologues: Orthologues: chimpanzee BMP7 (100% identical), macaque BMP7 (100% identical), pig BMP7 (98% identical), dog BMP7 (97% identical), mouse Bmp7 (97% identical), rat Bmp7 (97% identical), guinea pig BMP7 (97% identical), tropical clawed frog bmp7 (82% identical), zebrafish bmp7b (80% identical), zebrafish bmp7a (65% identical). Paralogues in human: BMP5 (66% identical), BMP6 (62% identical), BMP8A (48% identical), BMP8B (48% identical), BMP2 (28% identical), BMP4 (28% identical), GDF6 (26% identical), GDF2 (25% identical), BMP10 (25% identical), GDF5 (24% identical), GDF7 (23% identical), TGFB3 (23% identical), and 19 more.
Diseases named in the same sentence as BMP7 in open-access papers:
BMP7 is named in the same sentence as 262 diseases in open-access papers, as found by Europe PMC text mining. Sharing a sentence is not in itself a finding about the gene and the disease. The quoted sentences say what the papers report.
renal fibrosis (61 papers, 2006 to 2025). A final common manifestation of a wide variety of chronic kidney diseases characterized by glomerulosclerosis and tubulointerstitial fibrosis. "The role of BMP-7 in renal pathophysiology also has been confirmed by an in vivo study, which showed that when DKD rats were given exogenous recombinant BMP-7, renal fibrosis and podocyte loss were attenuated." (PMID 25790348, 2015). "BMP-7 administration reduced renal fibrosis, provided neuroprotection in ischemic stroke injury and Parkinson’s disease, and promoted bone regeneration, with no reported off-target toxicity." (PMID 41471266, 2025). "In contrast, the TGF-β family member, bone morphogenetic protein 7 (BMP-7), exerts an antifibrotic role in renal fibrosis." (PMID 40249927, 2025). "BMP-7-deficient mice usually die from perinatal renal failure, whereas recombinant BMP-7 alleviates renal fibrosis and acute renal failure by inhibiting inflammation and apoptosis." (PMID 36909186, 2023). "Patients with T2D have elevated urinary excretion of markers of tubular injury (RBP-4, GST-π), renal fibrosis (Col1, Col4), and antifibrotic growth factors (BMP-7, HGF)." (PMID 36836700, 2023). "Of interest, treatment with recombinant BMP-7 exerts renal protective effects because of a profound reduction in renal fibrosis." (PMID 36613483, 2022). "Bone morphogenetic protein-7 (BMP-7) ameliorates renal fibrosis by increasing the expression of SKIL in renal tubular epithelial cells." (PMID 36585417, 2022). "During renal fibrosis, BMP-7 plays a major role in inhibiting TIF with respect to decreasing apoptosis, maintaining tubular epithelial phenotype, and inhibiting ECM synthesis." (PMID 35314669, 2022). "For example, it was shown that miR-22 and BMP-7/6 form a regulatory feedback circuit in the course of renal fibrosis." (PMID 36139691, 2022). "Our previous results and other studies have confirmed that hyperglycemia decreased the mRNA and protein levels of BMP-7 in RTECs, and it was negatively correlated with renal fibrosis." (PMID 35314669, 2022). "During renal fibrosis, the effect of BMP-7 to impede the development of fibrosis involves reversing glomerular hypertrophy, reducing tubular atrophy, maintaining the tubular epithelial cell phenotype, delaying the EMT process, and inhibiting ECM synthesis." (PMID 35721136, 2022). "As the HDAC inhibitor, SFN prevents diabetes-induced renal fibrosis through epigenetic upregulation of BMP-7." (PMID 35721136, 2022). "BMP-7 is a physiologic antagonist of TFGβ, an essential bystander in renal fibrosis as a central event in the progression of CKD." (PMID 36613483, 2022). "In previous studies, BMP7 was reported to have beneficial effects in many fibrotic models including renal fibrosis and cardiac fibrosis, but BMP7 administration was insufficient to protect mice against bleomycin-induced pulmonary or skin fibrosis." (PMID 35864207, 2022). "As BMP-7 induces protection against TGF-β-mediated renal fibrosis, restoration of BMP-7 expression represents another major mechanism by which HDAC inhibition prevents progressive CKD." (PMID 33398599, 2021). "While bone morphogenetic protein-7 (BMP-7) has been studied for bone regeneration, it is now drawing great attention as a therapeutic for fibrotic diseases, including renal fibrosis." (PMID 33364962, 2020). "In support of a link between BMP and HDACs, previous work has also shown that HDACs act to suppress BMP-promoted astrogliogenesis in the embryonic forebrain and that HDAC-dependent transcriptional repression of Bmp-7 potentiates TGF-β mediated renal fibrosis." (PMID 31572723, 2019). "BMP7 have proven to be capable of reversing renal fibrosis in mice, EMT and in vitro profibrotic effects of TGF-β and Gremlin." (PMID 30386246, 2018). "The results showed that siRNA Klotho-treated mice displayed slight increase of renal fibrosis, phosphorylated Smad3 and reduced BMP-7." (PMID 28387374, 2017).
renal fibrosis (continued). "Recombinant BMP7 therapy has been shown to inhibit fibrosis progression in a variety of mouse models of renal fibrosis, including the STZ49 diabetic mice." (PMID 28294194, 2017). "BMP-7 is expressed only in select adult tissues, including the kidney, and its expression declines in rodent models of renal fibrosis." (PMID 28769795, 2017). "with previous studies on liver and renal fibrosis, suggesting that BMP-7 is one of the possible mechanisms in reversing liver fibrosis by counteracting TGF-β and EMT." (PMID 27199755, 2016). "Another study showed that renal fibrosis in mice was remarkably reversed by treatment with bone morphogenetic protein 7, which induced the transition of the dedifferentiated phenotype to the normal epithelial status." (PMID 27196561, 2016). "Opposing regulators of epithelial/mesenchymal phenotype in renal proximal tubule epithelial cells (PTEC), TGFβ1 and BMP7 also have counter-regulatory effects in models of renal fibrosis." (PMID 23320068, 2013). "It has been recently shown that exogenous administration of BMP7 reversed renal fibrosis in some animal models of CKD." (PMID 23300650, 2012). "Accordingly, BMP-7 has also been reported to inhibit many processes involving TGFβ1 including renal fibrosis, cardiac fibrosis and allograft rejection in vivo as well as EMT and at high concentrations, endothelial cell-mesenchymal transition." (PMID 19112509, 2008). "BMP-7 has been reported to inhibit renal fibrosis and TGFβ1-induced epithelial-mesenchymal transition (EMT), in part through negative interactions with TGFβ1 induced Smad 2/3 activation." (PMID 19112509, 2008). "It has been demonstrated that exogenous BMP-7 can reduce renal fibrosis, so exogenous BMP-7 might also inhibit tissue fibrosis and inflammation in the cornea after alkali burns." (PMID 40696418, 2025). "A long-acting carbohydrate-deficient BMP7 prepared by combining albumin fusion technology and site-specific mutagenesis showed a sustained renoprotective activity in the mice model of UUO-induced renal fibrosis and cisplatin-induced AKI." (PMID 35890230, 2022). "In addition, a small molecule AA-123 that mimics BMP-7 activity by activating ALK3 signaling reproduces the antifibrotic activity of recombinant BMP-7 in murine models of renal fibrosis." (PMID 35314669, 2022). "In addition, they inhibited the down-regulation of two renal fibrosis protective factors (klotho and BMP-7)." (PMID 36148005, 2022). "Moreover, recombinant BMP7 therapy inhibits fibrosis in several rodent models of renal fibrosis, including the STZ diabetic mouse." (PMID 34690762, 2021). "This indicates that, SAA canup-regulate BMP-7 and Smad6 expressions in renal tissue, which may be one of theimportant mechanisms of anti-renal fibrosis." (PMID 30843937, 2019). "BMP-7 is an important cytokine that inhibits the renal fibrosis." (PMID 30843937, 2019). "In addition, administration of rhBMP-7 (recombinant human BMP-7) or overexpression BMP-7 was able to suppress renal fibrosis during diabetic nephrophay." (PMID 27145860, 2016). "Nevertheless, since it has been shown that renal fibrosis could be at least ameliorated by BMP7 driving activation of its ALK3 receptor, we decided to explore them in NCAM+ interstitial cells." (PMID 26327314, 2015). "Therefore, amelioration of renal fibrosis by follistatin may be obtained by the enhancement of the antifibrotic effects of BMP-7." (PMID 24883308, 2014). "Class IIa HDAC inhibitor MC1568 inhibits EMT-mediated renal fibrosis by inhibiting the activation of TGF-β/SMAD3 and the NF-κb signaling pathway, and upregulating the expression of BMP-7, KLOTHO protein." (PMID 38929505, 2024). "HDAC8, identified as upregulated in the UUO model, is a promoter of renal fibrosis by influencing EMT-related pathways, inducing cell cycle arrest and suppressing the expression of BMP-7 and KLOTHO proteins." (PMID 38929505, 2024).
renal fibrosis (continued). "Renal fibrosis is mainly mediated by transforming the growth factor-β1 (TGF-β1) and bone morphogenetic protein-7 (BMP-7)." (PMID 35845802, 2022). "The bone morphogenetic protein-7 (BMP7) is capable of inhibiting TGF-β/Smad3 signaling, which subsequently results in protecting the kidney from renal fibrosis, but its lower blood retention and osteogenic activity are bottlenecks for its clinical application." (PMID 35890230, 2022). "TGF-β and the bone morphogenetic protein-7 (BMP7), two key members of the TGF-β superfamily, play important but diverse roles in renal fibrosis." (PMID 35890230, 2022). "In animal models of renal fibrosis, HDACs mainly promote the TGF-β1/Smad and inhibit the BMP-7/Smad pathway." (PMID 36148005, 2022). "BMP-7, a member of the TGF-β superfamily, protects against the TGF-β/Smad pathway during renal fibrosis." (PMID 36148005, 2022). "All these results suggested that OMT affected the BMP-7–MAPK pathway and thus improved the development of renal fibrosis in DKD." (PMID 35721136, 2022). "Under the action of heme oxygenase-1 (HO-1), bone morphogenetic protein-7 (BMP-7), and hepatocyte growth factor (HGF), renal fibrosis can be blocked or even reversed." (PMID 31781634, 2019). "The purpose of this study was to detect renal SWV and serum BMP-7 in different stages of DKD and to study the feasibility of these two parameters in the diagnosis of DKD renal fibrosis." (PMID 25790348, 2015). "Meanwhile, some other mediators are found to exert marked anti-fibrotic effects in the pathogenesis of renal fibrosis, such as HGF (hepatocyte growth factor), EPO (erythropoietin) and BMP-7 (bone morphogenetic protein-7)." (PMID 24844766, 2014). "BMP-7 is the antagonist of TGF-β1 signalling and has been found to inhibit TGF-β1-induced renal fibrosis by reversing EMT process." (PMID 24949470, 2014). "Many studies have demonstrated that TGF-β promotes renal fibrosis through EMT by activation of Smad2/3 and was counteracted with BMP-7 by motivation of Smad1/5/8 to maintain the epithelial phenotype of TECs." (PMID 24350257, 2013). "However, as is abundantly clear from the extensive body of pre-clinical literature generated that suggest therapeutic potential of BMP-7 in the context of SLE, renal injury and renal fibrosis, BMP-7-based therapies in other contexts should remain a priority." (PMID 37626268, 2023). "Herein, we asserted that BMP-7 upregulates SnoN mRNA and protein levels by activating the classical Smad1/5 pathway to refrain from the partial EMT of RTECs and the deposition of ECM in diabetes-induced renal fibrosis." (PMID 35314669, 2022). "Similarly, a number of publications have demonstrated that emodin retarded renal fibrosis by modulating several pathways, such as TGF-β/Smad, TGF-β/BMP-7, PI3K/Akt/GSK-3β, and Bax/caspase-3 signaling pathways." (PMID 35002735, 2021). "TGF-β1 has been deemed to serve as the predominant mediator of the pathology of renal fibrosis, whereas interferon-γ (IFN-γ), hepatocyte growth factor (HGF) and bone morphogenetic protein 7 (BMP-7) inhibit the production of matrix components primarily by counteracting TGF-β1 action." (PMID 34356613, 2021). "HDAC inhibitors induce BMP7 and inhibit TGF-β-induced renal fibrosis." (PMID 34389355, 2021). "Several previously reported protective genes (hypoxia inducible factor 1, HIF-1α; heme oxygenase 1; HO-1, colony-stimulating factor 2, CSF-2; bone morphogenetic protein-7, BMP-7; and activin-like kinase 3; ALK3) against renal fibrosis progression after ischemia reperfusion were evaluated after IR." (PMID 34302012, 2021). "We also found that DSS abrogated UUO-induced renal fibrosis by Masson's staining and collagen volume fraction (CVF) analysis; this is consistent with the western blot analysis that showed DSS abrogated the UUO-induced enhanced TGF-β1 and weakened BMP-7." (PMID 31007700, 2019).
renal fibrosis (continued). "Obviously, DSS could prevent the rise in TGF-β1 and decline in BMP-7 induced by UUO, suggesting that DSS is able to attenuate renal fibrosis." (PMID 31007700, 2019). "Upregulation of FSP1, Col1a1, and Vim has been implicated in renal fibrosis and the downregulation of the antifibrotic BMP4 and BMP7 confirmed the fibrosis establishment, while central role of TGF-β in human and experimental models for renal fibrosis has been well described." (PMID 24995284, 2014). "This is also of relevance as recent in vivo and in vitro studies have shown that renal fibrosis can be reversed by administration of BMP-7, indicating that, if EMT does play a role in RA, BMP-7 might be an interesting therapeutic drug." (PMID 17076892, 2006). "In addition, HDAC inhibitors induce BMP7 and inhibit TGF-β-induced renal fibrosis." (PMID 34389355, 2021). "In this regard, systemic injection of BMP7 (a TGF-β antagonist) reverses renal fibrosis in mice and paricalcitol (a synthetic vitamin D analog that suppresses the expression of TGF-β and the Type I TGF-β receptor) attenuates ureteral obstruction-induced renal fibrosis in mice." (PMID 29271928, 2017). "In unilateral ureteral obstruction mice, weekly dosing of HSA-BMP7 significantly attenuated renal fibrosis, but the individual components, i.e., HSA or BMP7, did not." (PMID 35890230, 2022).